MIR8080 (microRNA 8080)
Synonyms: hsa-mir-8080
Gene: MicroRNA gene on chromosome 2 (79,866,495 to 79,866,583, reverse strand). Ensembl gene ENSG00000276917.
Homologues: Orthologues: chimpanzee MIR8080 (100% identical).